CST3 (cystatin C)
Diseases named in the same sentence as CST3 in open-access papers (continued):
Sharing a sentence is not in itself a finding about the gene and the disease.
acute kidney injury (continued). "It is vital to note that the creatinine and cystatin C methods of estimating GFR discussed here are not validated for use in acute kidney injury (AKI)." (PMID 28913589, 2017). "Although serum cystatin C (sCysC), urinary N-acetyl-β-d-glucosaminidase (uNAG), and urinary albumin/creatinine ratio (uACR) are clinically available, their optimal combination for acute kidney injury (AKI) detection and prognosis prediction remains unclear." (PMID 28264714, 2017). "Our results indicate that, in cancer patients receiving platinum-based chemotherapy, baseline cystatin C serum level does not predict renal failure." (PMID 28078200, 2016). "Many reports emphasize that serum cystatin C is a better indicator of GFR than serum creatinine concentration both in patients with chronic kidney damage including chemotherapy) and in patients with acute kidney injury: in papers by Liang and Krawczewski." (PMID 27325303, 2016). "In conclusion, serum cystatin C is not a reliable early marker to efficiently predict renal failure in patients receiving chemotherapy." (PMID 28078200, 2016). "Cystatin-C, angiotensinogen, NGAL, and KIM-1 are known markers of acute kidney injury." (PMID 27672664, 2016). "Serum levels of the biomarkers were correlated with risk of AKI and the Acute Kidney Injury Network (AKIN) stage and all significantly discriminated AKI (area under the receiver operating characteristic [ROC] curve: BNP: 0.86, sST2: 0.74, NGAL: 0.75, cystatin C: 0.73; all P < 0.05)." (PMID 25853556, 2015). "However, cystatin C has been reported to be a better marker of renal failure in older adults compared to serum creatinine, mainly in those with low creatinine, which could reinforce cystatin C as a marker not only of renal failure, but also may be an indicator of death in this population." (PMID 24967238, 2013). "As cytokines, plasma variations of cystatin C during IRRT for septic shock-related acute renal failure have not been studied." (PMID 20546598, 2010). "Because of a significant decrease in p cystatin C during HD, this should not be considered as an accurate marker for residual glomerular filtration rate during septic acute renal failure when receiving HD with a PMMA hemodialyzer." (PMID 20546598, 2010). "Under the light of current observations, Pb-exposed workers experience proximal tubular injury (KIM-1, NAG) and dysfunction (β2μG, α1μG, Cystatin-C), prior to onset of obvious renal failure, as evidenced by e-GFR & serum creatinine levels not significantly differing from controls." (PMID 39717854, 2024). "In practical terms, the measurement of cystatin C-based estimated GFR, which remains unaffected by medications inhibiting creatinine secretion, may assist in distinguishing nephrotoxicity from pseudo-acute kidney injury." (PMID 38915820, 2024). "HS resulted in an acute kidney injury (AKI) defined as a significant increase in plasma creatinine, urea (BUN), and cystatin C levels compared to the sham group." (PMID 34353366, 2021). "Urinary NGAL, KIM, L FABP-1, Cystatin C, and IL18 were proposed as tools for early detection of acute kidney injury (AKI) but the determination of their validities and clinical utility is still in progress." (PMID 30643824, 2018). "Baseline cystatin C values were not able to predict renal failure during subsequent treatment." (PMID 28078200, 2016). "Finally, we showed that cystatin C is not a marker of acute kidney injury in elderly patients hospitalized in the intensive care unit when used AKIN as standard diagnostic criteria." (PMID 24967238, 2013). "Furthermore, there is evidence that serum Cystatin C concentrations may increase before serum Cr in acute kidney injury (AKI) but that Cys C concentrations decrease before creatinine in many hospitalized patients, being a biomarker of AKI recovery in hospitalized patients." (PMID 35269664, 2022).
acute kidney injury (continued). "However, the positive effects of creatinine and cystatin C observations on iohexol clearance estimates might be limited in clinical scenarios with a strong GFR dynamic, such as acute kidney injury, due to a discrepancy between creatinine and cystatin C concentrations with actual GFR." (PMID 34811403, 2021). "Percentage of detection of acute kidney injury (AKI) using the criteria proposed by the IRIS and through the serum concentration of cystatin C in dogs during their stay in the intensive critical unit (ICU) of the Veterinary Hospital of the Federal University of Minas Gerais (UFMG)." (PMID 34820434, 2021). "Could metabolism be impaired in renal failure, or does cystatin C reflect a nonrenal signal?" (PMID 30363702, 2018). "A worsening of renal function estimated by enhanced Cystatin-C rather than by creatinine has been recently described in septic patients with acute kidney injury (AKI) presenting higher Cystatin C levels than non-AKI septic patients." (PMID 29703925, 2018). "Cystatin-C and NGAL are confirmed as biomarkers for acute kidney injury (AKI)." (PMID 25535078, 2014). "Cystatin C is not affected by age, gender, muscle mass, or ethnicity and is more sensitive than GFR in detecting acute kidney injury, and it is a biomarker for cardiovascular disease and for CKD." (PMID 38732117, 2024). "Additionally, pooled analysis showed that Cystatin C levels in patients with acute kidney injury (AKI) was 1.562 ± 0.885 mg/dL, compared to 0.811 ± 0.108 mg/dL for patients without AKI (SMD = 4.56; 95%CI: 0.27 to 8.85; p = 0.04)." (PMID 36361485, 2022). "Urinary excretion of identified biomarkers of acute kidney injury, namely L-FABP, cystatin C and NAG, but not KIM-1, increased abruptly after the onset of PD feeding, and increments were significant on the following day, in advance of increments in UAE." (PMID 26606054, 2015). "Thus, creatinine is not an optimal marker for detection of acute renal failure in intensive care patients; there is on-going search for better GFR markers, and cystatin C and proANP (Atrial natriuretic peptide) have been suggested as alternatives." (PMID 21067456, 2011). "Additionally, among the patients without acute kidney injury (AKI), the sarcopenia index, considered as serum creatinine-to-serum cystatin C ratio, might be helpful in muscle mass estimation and following its changes." (PMID 38999759, 2024).
Hypertension (152 papers, 2008 to 2026). The presence of chronic increased pressure in the systemic arterial system. "Univariable logistic regression analysis identified several variables significantly associated with EA-POD1PN, including age, hypertension, cystatin C, urea nitrogen, tumor size, and intraoperative blood loss." (PMID 40452832, 2025). "After adjusting for potential confounding factors, including age, hypertension, smoking history, education, triglyceride, and cystatin C, PI remained a significant independent risk factor (p < .001) for a high burden of CSVD." (PMID 38783554, 2024). "Our analyses revealed notable associations of PGS for cardiovascular disease, hypertension, and cystatin C levels with breast cancer survival outcomes." (PMID 37377609, 2023). "The findings revealed significant associations of PGS for cardiovascular disease, hypertension, and cystatin C levels with several breast cancer survival outcomes." (PMID 37377609, 2023). "Univariate analysis suggested that age, male, smoking, hypertension, cystatin C, homocysteine, and FHS were risk factors for the severity of PWMH." (PMID 37239307, 2023). "In males, homocysteine (log10) was positively associated with hypertension (r = 0.569, P < 0.001), creatinine (r = 0.367, P < 0.001) and cystatin C (log10) (r = 0.333, P = 0.001)." (PMID 37587534, 2023). "With respect to notable findings in our analysis, we highlight the associations of breast cancer survival with CVD, hypertension, and cystatin C levels." (PMID 37377609, 2023). "In the current study, only 3 genes associated with hypertension (Ephx2, Cst3 and Ltbp2) appeared on the list of the top 40 DEGs that make the largest contribution to inter-strain differences." (PMID 26822062, 2016). "According to RGD annotations, there were several genes related to CNS diseases (Abcg2, Ephx2, RGD1563482, Tgfb2, Mal, and Cst3), and 3 genes associated with hypertension (Ephx2, Cst3, and Ltbp2) are found on this list." (PMID 26822062, 2016). "Accumulating evidence suggests that elevated cystatin-C levels are associated with several cardiovascular conditions, including coronary heart disease, stroke, myocardial infarction, heart failure, and hypertension." (PMID 41221210, 2025). "Compared with absent or mild WMH (Fazekas 0–1), Group comparisons revealed that advanced age, hypertension, and abnormal renal function markers [creatinine, cystatin C, β2-microglobulin (β2-MG)] were common risk factors for moderate–severe WMH (all p < 0.0001)." (PMID 40937180, 2025). "In the largest, most contemporary Mendelian randomization analysis for metabolic traits and breast cancer survival outcomes, we identified associations between PGS for CVD, cystatin C levels, and hypertension in relation to breast cancer survival outcomes at a nominal statistical significance level." (PMID 37377609, 2023). "Furthermore, cystatin C provides incremental information for the risk stratification of female objects age range 55 to 65 years old, accompany with hypertension or with higher BMI." (PMID 37817071, 2023). "Multiple linear regression analysis, adjusted for age, gender, EAT, max IMT, CACS, baPWV, HbA1c and the presence of hypertension, revealed age, male, EAT and the presence of hypertension to show independent statistically significant associations with cystatin C." (PMID 28922364, 2017). "Of the top 40 DEGs making the greatest contribution to the interstrain differences, there were 3 genes (Ephx2, Cst3 and Ltbp2) associated with hypertension that were considered to be suitable for further studies as potential targets for the stress-sensitive hypertension therapy." (PMID 26822062, 2016). "In the current study, we defined 3 genes associated with hypertension (Ephx2, Cst3 and Ltbp2) that might be of interest for further studies as potential therapeutic targets for stress-sensitive hypertension therapies." (PMID 26822062, 2016).
Hypertension (continued). "Second, cystatin C is highly correlated with hypertension, and the observed association between cystatin C and LV remodeling could be the result of adjustment by imprecise measures of blood pressure leading to residual confounding." (PMID 21977320, 2011). "Cystatin C levels are inversely associated with LV end diastolic and systolic volumes and directly associated with concentricity independent of traditional cardiovascular risk factors including hypertension in a multi-ethnic population." (PMID 21977320, 2011). "Compared with levels <0.718 mg/L, cystatin C levels of 0.718–0.932 mg/L and >0.932 mg/L were linked to higher risks, particularly among individuals aged >59 years (HRs: 1.545 and 3.458), current smokers (1.484 and 2.201), and those with hypertension (1.401 and 2.279)." (PMID 40983592, 2025). "However, reverse causation in the relationship of cystatin C and blood pressure is possible, as there is some evidence from previous studies that cystatin C may be caused by hypertension and vice versa." (PMID 34588554, 2021). "Multivariate regression revealed that norepinephrine, normetanephrine, metanephrine, serum uric acid, serum creatinine, duration of hypertension, and cystatin C were independent predictors of organ damage (all P < 0.05)." (PMID 41169460, 2025). "We report a 65-year-old man with a history of benign prostatic hyperplasia, hypertension, and obstructive sleep apnea who had an elevated serum creatinine level and normal cystatin C in the setting of L-arginine supplementation." (PMID 41194845, 2025). "Univariate analysis showed statistically significant differences between the two groups in the following parameters: norepinephrine, normetanephrine, metanephrine, serum uric acid, serum creatinine, duration of hypertension, and cystatin C (all P < 0.05)." (PMID 41169460, 2025). "Significant factors associated with early postoperative ambulation included age, hypertension, tumor size, serum cystatin C, blood urea nitrogen, renal artery clamping time, and intraoperative blood loss." (PMID 40452832, 2025). "Patients in the higher serum cystatin-C group were older, more likely to suffer from several comorbidities, including New York Heart Association (NYHA) III/IV, hypertension, vascular diseases, and atrial fibrillation." (PMID 41221210, 2025). "Multivariable logistic regression confirmed norepinephrine, normetanephrine, metanephrine, serum uric acid, serum creatinine, hypertension duration, and cystatin C as independent predictors of hypertensive organ damage." (PMID 41169460, 2025). "Hypertension, serum albumin, baseline creatinine and baseline cystatin C were significant predictors of renal recovery in the studied patients (p = 0.017, 0.006, 0.030, and < 0.001, respectively)." (PMID 40707908, 2025). "After adjusting for hypertension, the link of hypertension and eGFRcystatin c (OR = 1.002, 95%CI: 0.997–1.007, P = .500) and cystatin C levels (OR = 0.988, 95% CI: 0.960–1.015, P = .378) lost statistical significance." (PMID 39928765, 2025). "Firstly, in a group without DM, consisting of 8,224 participants, the analysis adjusted for factors such as age, CRP, eGFR, sex, HDL-c, LDL-c, UA, CLD, PLT, Cystatin C, hypertension, HBA1C, CKD, smoking, drinking status." (PMID 38402161, 2024). "Apart from addressing traditional well-known factors (such as tobacco use, unhealthy diet, and hypertension), cystatin C monitoring from the kidney function aspect provides another risk enhancer accounting for the residual risk of stroke." (PMID 38681764, 2024). "The high‐burden group exhibited a higher average age, greater prevalence of smoking and hypertension, and lower education level, triglycerides, high‐density lipoprotein, cystatin C, and PI compared to the low‐burden group (p < .05)." (PMID 38783554, 2024). "The objective of this study was to explore the association between the ratio of serum creatinine to cystatin C to waist circumference (CCR/WC) and hypertension." (PMID 38752178, 2024).
Hypertension (continued). "It is noteworthy that cystatin C alone determined over half of the variability of homocysteine levels in females in the full model including cystatin C and hypertension as independent regressors." (PMID 37587534, 2023). "Cluster 7 was characterized by renal function (cystatin C and creatinine) levels and had a high prevalence of a history of stroke (32.7%), sICAS (33.34%), hypertension (86.9%), CHD (24.8%), urinary tract infection (15%), and renal insufficiency (0.7%)." (PMID 37248226, 2023). "Future studies with larger groups of subjects are needed to explore the sex-related relationship of hypertension, cystatin C and hyperhomocysteinemia in ACS patients with normal renal function." (PMID 37587534, 2023). "A prospective cohort study showed that for every 0.2 mg/L increase in the plasma cystatin C, the incidence of hypertension increased by 15%." (PMID 37663661, 2023). "Elevated serum B2M, cystatin C, and LCN-2 levels were associated with being male, overweight/obesity, hypertension, alcohol consumption and smoking." (PMID 37155257, 2023). "Univariate analysis suggested that age, smoking, hypertension, cystatin C, homocysteine, hsTnI, proteinuria, uric acid, and FHS were risk factors for the severity of DWMH." (PMID 37239307, 2023). "PGS for three of the traits tested were associated with one or more survival outcomes at a nominal significance level of P < 0.05, which included CVD, serum cystatin C levels, and hypertension." (PMID 37377609, 2023). "The main determinants of fasting plasma homocysteine levels were hypertension and creatinine in men while cystatin C and hypertension in women in ACS patients with normal renal function." (PMID 37587534, 2023). "In this study, we found that the factors associated with homocysteine levels in males were hypertension, creatinine and cystatin C while in females, the factors were age, hypertension, LDL-C, Apo B, creatinine, cystatin C and UA." (PMID 37587534, 2023). "Multiple stepwise regression analysis showed that after adjusting for confounding factors, cystatin C (log10) (P = 0.004) and hypertension (P = 0.005) were independently related to homocysteine (log10) in women." (PMID 37587534, 2023). "B2M, cystatin C and LCN-2 were all significantly associated with sex, overweight/obesity, hypertension, alcohol consumption and smoking." (PMID 37155257, 2023). "CST3 was also used as a potential biomarker to measure the efficacy of valsartan in the treatment of hypertension for patients with kidney dysfunction (NCT00140790)." (PMID 36814924, 2023). "The elevated cystatin C is indicative of renal impairment in metabolically unhealthy obese due to hypertension, hyperlipidemia and dysglycemia." (PMID 38092892, 2023). "Univariate analysis suggested that age, gender, smoking, hypertension, TC, LDL, cystatin C, hsTnI, homocysteine, and FHS are risk factors for the severity of WMH." (PMID 37239307, 2023). "In women, cystatin C (log10) (P = 0.004) and hypertension (P = 0.005) were independently related to homocysteine (log10)." (PMID 37587534, 2023). "In multivariate regression analysis, the variables that remained associated with higher NT-proBNP at both measurement time points were older age, female sex, a history of hypertension, and higher cystatin C concentrations." (PMID 33562838, 2021). "Our results indicated that the levels of urea nitrogen and cystatin C were increased in COVID-19 patients with hypertension." (PMID 33557785, 2021). "We also found a significant association at the PDILT/UMOD locus (lead SNP rs77924615), that colocalises with hypertension, cystatin C, creatine, and kidney and urinary calculus in the UKBB." (PMID 34128465, 2021). "In summary, serum cystatin C levels in patients with hypertension are significantly elevated, and are closely related to the occurrence of CHD and the severity of CHD." (PMID 32481372, 2020).